AKT1 (AKT serine/threonine kinase 1)
Diseases named in the same sentence as AKT1 in open-access papers (continued):
Sharing a sentence is not in itself a finding about the gene and the disease.
renal fibrosis (58 papers, 2013 to 2026). A final common manifestation of a wide variety of chronic kidney diseases characterized by glomerulosclerosis and tubulointerstitial fibrosis. "Recent research indicates that mice with AKT1 gene knockdown exhibit lower levels of renal fibrosis after unilateral ischemia-reperfusion injury (IRI) compared to wild-type mice." (PMID 37171332, 2023). "Recently, a skeletal muscle-specific Akt1 transgenic (Akt1 TG) mouse can prevent the skeletal muscle loss by UUO, and its effect mitigated the renal fibrosis within the kidney, in which Akt1 was preserved." (PMID 33299873, 2020). "AKT1 is a key target of renal fibrosis involved in the transition from acute kidney injury to CKD." (PMID 40391375, 2025). "Some experimental results showed that Akt was over expressed in the kidney of diabetic rats, and liraglutide could reduce the expression level of Akt1, hinder renal fibrosis, relieve oxidative stress and improve diabetic nephropathy." (PMID 34740995, 2021). "Thus, in this study, we investigated the role of Akt1, one of the three Akt isoforms, in renal fibrosis and tubular apoptosis using the murine model of UUO." (PMID 33299873, 2020). "Conclusively, these results suggest that the deletion of Akt1 may contribute to renal fibrosis via induction of the TGFβ1/STAT3 pathway in a murine model of UUO." (PMID 33299873, 2020). "Combined with the results of our network pharmacology, that is, both AKT1 and IL‐6 have a good binding ability with various active ingredients of GBXZF, we speculated that GBXZF could reduce the inflammatory response and improve renal fibrosis by upregulating the PI3K/AKT signaling pathway." (PMID 41245191, 2025). "To study SSLF's functional mechanism and understand its potential inhibitory role in renal fibrosis, first, we found that STAT3, VEGFA, and AKT1 of the intersection genes of SSLF and RIF are the core proteins in the intersection genes." (PMID 35399631, 2022). "In molecular docking assays, the hydroxy saffron yellow pigment A isomer also showed vigorous binding activity with AKT1 and JUN, indicating that it can intervene in the inflammatory pathway and has good potential to reduce the inflammatory response and thus ameliorate renal fibrosis." (PMID 41245191, 2025). "Among them, AKT1 and IL‐6 are the core targets and key downstream factors of the PI3K/AKT inflammatory pathway, respectively, which suggests that the mechanism of action of Solid Formula to improve renal fibrosis may be related to the PI3K/AKT pathway." (PMID 41245191, 2025).
Sepsis (58 papers, 2009 to 2026). Sepsis is defined as life-threatening organ dysfunction caused by a dysregulated host response to infection. "GO and KEGG enrichment analyses provide compelling evidence for AKT1’s central role in sepsis-associated intestinal barrier dysfunction through multiple interconnected mechanisms." (PMID 40885907, 2025). "This is supported by our findings that the expression pattern of AKT1 was consistent with that of BCL2 in both sepsis and COVID-19." (PMID 41411324, 2025). "The gene differential expression analysis showed that compared with the healthy group, the sepsis patient group exhibited significantly lower expression levels of AKT1 and BCL2, but significantly higher expression levels of MMP9, ICAM1, TLR4, and HIF1A." (PMID 41411324, 2025). "The activation of AKT1 can promote apoptosis and inflammatory responses, accelerating the progression of sepsis." (PMID 39823512, 2025). "For instance, Reduning was found to reduce sepsis-induced lung injury through AKT1 targeting to suppress apoptosis in lung microvascular endothelial cells." (PMID 38678068, 2024). "In sepsis, downregulation of AKT1 regulates inflammatory responses and plays a role in immunosuppression." (PMID 36062176, 2022). "Our present study showed the reverse expression profiling between the ANXA1 (up) and AKT1 (down) in the neutrophil samples from patients with sepsis-induced immunosuppression." (PMID 33761636, 2021). "Taken together, EZH2 regulated export from the nucleus of BRCA1 in skeletal muscle cells of sepsis via regulating the extent of AKT-1 phosphorylation." (PMID 31830649, 2020). "Western blot analysis was performed to detect the extent of AKT-1 phosphorylation in skeletal muscle cells of sepsis." (PMID 31830649, 2020). "This study also demonstrated that HTS is a simple and effective way to explore new therapeutic agents, and our discovery of this novel AKT1 activator may provide a new treatment for sepsis." (PMID 36579349, 2022). "AKT1 is an important target in sepsis acute lung injury (SALI)." (PMID 36579349, 2022). "Combined with the results of network pharmacology analysis, it was illustrated that inhibiting the PI3K/AKT signaling pathway could activate apoptosis in sepsis, while RDN may activate this pathway by targeting AKT1, thus improving apoptosis and slowing down endothelial cell injury." (PMID 35903333, 2022). "Moreover, AKT1 has been reported functionally related with sepsis." (PMID 33959663, 2021). "Together, these results suggest AKT1 may play important roles in the development of sepsis." (PMID 33959663, 2021). "The expression trends of AKT1 and HIF1A in COVID-19 patients were consistent with those in sepsis patients." (PMID 41411324, 2025). "In our study, 6 key target genes involved in sepsis and COVID-19 treatment with JHD were identified including AKT1, MMP9, ICAM1, TLR4, BCL2 and HIF1A based on PPI network." (PMID 41411324, 2025). "AKT1 and STAT3 have been demonstrated as key genes in pyroptosis in sepsis, with high expression levels observed in lung tissue and lymphocytes." (PMID 39823512, 2025). "Among them, BCHE, AKT1, and IL2 are involved in the sepsis pathway, and LGALS3 is involved in both the sepsis and glycocalyx pathways." (PMID 36062176, 2022). "The deregulation of DEGs including AKT1 (down), IFN-inducible protein 6 (IFI6, down), IL-15 (up), and ANXA1 (up) was verified in the neutrophils from patients with sepsis-induced immunosuppression as compared with controls." (PMID 33761636, 2021). "AKT1, top up- (FKBP5, SORT1, VNN1, and CST7) and downregulated (PRR5L, SH2B3, SULF2, PLEKHO1, and PTPN6) genes in sepsis were validated using RT-PCR." (PMID 33959663, 2021). "Taken together, lncRNA MALAT1 interacting with EZH2 stimulated AKT-1 phosphorylation and decreased BRCA1 expression, consequently aggravating the progression of sepsis, highlighting a promising therapeutic option for sepsis." (PMID 31830649, 2020).
Sepsis (continued). "Flow cytometry was used to detect apoptosis of skeletal muscle cells of sepsis, which revealed that sh-MALAT1 + oe-EZH2 + sh-AKT-1 significantly inhibited cell apoptosis as compared with sh-MALAT1 + oe-EZH2." (PMID 31830649, 2020). "A recent study further showed that luteolin (20 mg/kg) inhibits the AKT1/nitric oxide synthase 2/cathepsin G (AKT1/NOS2/CTSG) axis, thereby blocking caspase-11 and GSDMD activation, leading to reduced IL-1β and TNF-α release, thus mitigating sepsis-induced pulmonary injury." (PMID 41394141, 2025). "Within the PI3K-AKT pathway framework, AKT1 enhances the anti-apoptotic function of BCL2 gene by phosphorylating and inhibiting pro-apoptotic proteins, highlighting the synergistic role of these two genes in regulating the immune response to sepsis and COVID-19." (PMID 41411324, 2025). "To further determine whether 6 key target genes identified in this study (AKT1, MMP9, ICAM1, TLR4, BCL2, and HIF1A) could be used as therapeutic targets for sepsis and COVID-19, we downloaded the gene expression profiles of sepsis and COVID-19 patients from the GEO database (GSE95233, GSE171110)." (PMID 41411324, 2025). "• Constitutive Akt1 signaling contributes to proliferation, activation, and selection of thymocytes by promoting signaling downstream of TCR.• myrAkt mice accumulate memory-phenotype CD4+ T cells, B cells, and develop both tumors and autoimmunity.• Akt overexpression improves survival during sepsis." (PMID 36081513, 2022). "lncRNA MALAT1 interacting with EZH2 promoted the extent of AKT-1 phosphorylation and decreased BRCA1 expression and export from the nucleus, thus promoting skeletal muscle cell apoptosis and inflammatory responses and ultimately accelerating the progression of sepsis." (PMID 31830649, 2020). "Hence, the current study was designed with the aim of investigating the potential role of lncRNA MALAT1 in the initiation and development of sepsis, and we have demonstrated that lncRNA MALAT1 functions through the EZH2/BRCA1/AKT-1 axis to affect the progression of sepsis." (PMID 31830649, 2020).
esophageal squamous cell carcinoma (57 papers, 2015 to 2025). Esophageal squamous cell carcinoma (ESCC) is a type of esophageal carcinoma (EC) that can affect any part of the esophagus, but is usually located in the upper or middle third. "As far as esophageal cancer is concerned, the expression level of AKT1 has been reported to be significantly elevated in tumor tissue of patients with esophageal squamous cell carcinoma." (PMID 33273919, 2020). "Other research has failed to associate the (rs2494750)AKT1 gene with squamous cell carcinoma of the esophagus or withcancer of the endometrium (Fallah etal., 2015)." (PMID 32484847, 2020).
esophageal cancer (56 papers, 2014 to 2025). A primary or metastatic malignant neoplasm involving the esophagus. "RUNX2 plays an oncogenic role in esophageal carcinoma by activating the PI3K/AKT1 and extracellular-regulated kinase signaling pathways." (PMID 33365318, 2020). "Similarly, lncRNA EIF3J-AS1 acts as an oncogene and induces AKT1 expression in esophageal cancer to promote cell invasion and metastasis." (PMID 40457415, 2025). "Additionally, dihydroartemisinin showed anticancer effects against esophageal cancer by inhibiting cell migration, inducing autophagy and cell cycle arrest, and targeting AKT1, p70S6K, and human telomerase reverse transcriptase." (PMID 39202965, 2024). "In esophageal carcinoma cell lines, high MCM7 expression induced cell proliferation, colony formation and migration by regulating the AKT1/mTOR messenger system." (PMID 34144903, 2022). "Silencing of MCM7 inhibited the phosphorylation of AKT1 and mTOR in both esophageal cancer cell lines, suggesting that MCM7 might promote cancer development and poor survival outcomes via activating the AKT1/mTOR signaling pathway." (PMID 32089988, 2020).
COVID-19 (55 papers, 2020 to 2025). A disease caused by infection with severe acute respiratory syndrome coronavirus 2. "Peripheral blood samples and sociodemographic data from 508 individuals with COVID-19, measuring plasma cytokine concentrations using ELISA and genotyped the AKT1 variants." (PMID 39439795, 2024). "In this study, we aimed to investigate the rs2494746 and rs1130214 variants in the AKT1 gene associated with severe COVID-19 outcomes." (PMID 39439795, 2024). "This study is pioneering in highlighting the impact of genetic variants of the AKT1 gene on the more unfavorable prognosis of COVID-19." (PMID 39439795, 2024). "The study analyzed the association between the rs1130214 and rs2494746 variants of the AKT1 gene with the severity of COVID-19." (PMID 39439795, 2024). "Based on the maximum degree value, TNF and AKT1 were respectively identified as the core targets in the network of COVID-19 pathogenic targets and the network of LHQW therapeutic targets." (PMID 34731090, 2021). "This is the first study that correlates variants on the AKT1 gene with COVID-19." (PMID 39439795, 2024). "Therefore, this study aimed to investigate the association between variants in the AKT1 gene and worse outcomes of COVID-19." (PMID 39439795, 2024). "Therefore, the XBJ injection can regulate the TNF signal pathway through AKT1, so that it has anti-inflammation and anti-virual effects, and thus the potential to reduce the inflammation caused by COVID-19." (PMID 34077310, 2021). "The XBJ injection may inhibit the lipopolysaccharide-mediated inflammatory response, modulate NOS activity, and regulate the TNF signaling pathway by affecting the function of the AKT1, thereby ultimately suppressing the excessive inflammatory response associated with COVID-19." (PMID 34077310, 2021). "AKT1 is a key participant in COVID-19-related immune inflammation, while PTGS2 inhibition reportedly regulates the excessive inflammatory response of COVID-19." (PMID 41477204, 2025). "They identified 40 intersection targets between cepharanthine and COVID-19, with key targets primarily involving Src, AKT1, EGFR, and mTOR, among others." (PMID 41303371, 2025). "Similar to the EGFR state observed in mild COVID-19, we also detected altered expression of Bcl2, AKT1, and MAPK8." (PMID 39502570, 2024). "There were three target genes (JUN, RELA, and AKT1) with a greater degree of significance, and they were identified as potentially relevant genes involved in the processes of HLJDD therapy of COVID-19-associated AKI." (PMID 37533739, 2023). "AKT1 activation increases inflammatory and metabolic responses, making it a suitable target for COVID-19 therapy." (PMID 37347115, 2023). "Comparative analysis of two peptides has shown that they have common binding sites in the AKT1 and AKT2 genes, the protein products of which are functionally associated with the development of the cytokine storm in COVID-19." (PMID 37686182, 2023). "Recent studies show that the AKT1 gene is one potential drug target for COVID-19 treatment and also has a greater involvement in SARS-CoV-2 viral infection related complexity." (PMID 36016137, 2022). "The results of the KEGG pathway analysis showed that AKT1 was involved in the treatment of COVID-19, mainly by regulating TNF and other signaling pathways." (PMID 34077310, 2021). "Among the Hubgenes, AKT1 was the first one with the tightest connection, which may mediate the level of inflammatory factors in COVID-19." (PMID 36701702, 2023). "The underlying mechanisms of kaempferol against COVID-19/PF co-occurrence may be related to bind to EGFR, SRC, MAPK3, MAPK1, MAPK8, AKT1, RELA and PIK3CA." (PMID 35754492, 2022). "The ACE-AngII-AT1 axis may be activated in the COVID-19 patients, given that there was a higher immunoexpression of AKT-1 and TGF-β1 in those patients compared to the CONTROL group." (PMID 35008594, 2021).
COVID-19 (continued). "Despite all these findings, it has not been reported whether these three active ingredients relieve COVID-19 symptoms through the direct regulation of AKT1." (PMID 34077310, 2021). "In this study, 38 non-repeated active ingredients and 206 non-repeated potential targets of the XBJ injection, 277 potential targets of COVID-19, and 46 junction targets were screened using network pharmacology analysis, and the core target from the junction targets was identified to be AKT1." (PMID 34077310, 2021). "Recent research has demonstrated that Akt1 is a key target for LHQW to treat COVID-19." (PMID 34721017, 2021). "Furthermore, complete transcriptome RNA sequencing of the peripheral blood of COVID-19 patients revealed that AKT1 is one of the central genes in the differential gene PPI network." (PMID 34803696, 2021). "Interestingly, AKT1 is also noted as a potential therapeutic target in COVID-19 management." (PMID 40420184, 2025). "Its active compounds beta-carotene, kaempferol, luteolin, naringenin, quercetin, and wogonin, could target RAC-alpha serine/threonine-protein kinase (Akt1), which is involved in lung injury, lung fibrogenesis, and virus infection, thereby helping eliminate virus infection with COVID-19." (PMID 34861881, 2021). "And the key targets of these important pathways, such as AKT1, PIK3CA, PIK3CD and CEP, all have good binding energy, which reveals that CEP treats COVID-19 mainly by acting on these key targets and regulating related pathways." (PMID 35935817, 2022). "There was also a significant increase observed in the immunoexpression of tissue biomarkers ACE-2, AKT-1, CD44v6, IL-4, MMP-9, α-SMA, Sphingosine-1, and TGF-β1 in the COVID-19 group." (PMID 35008594, 2021). "According to the results of the KEGG pathway analysis, the TNF signaling pathway is the most significant pathway in which the core target AKT1, that is the core target of junction targets to XBJ injection and COVID-19, was involved." (PMID 34077310, 2021). "No statistical difference was observed in the tissue expression of AKT-1, Cav-1, MMP-9, Sphingosine-1, and TGF-β1 when testing COVID-19 and H1N1 groups." (PMID 35008594, 2021). "According to the results of the GO enrichment analysis, the response to lipopolysaccharide (LPS) was the most significant biological process that AKT1, the core target of junction targets to the XBJ injection and COVID-19, was involved." (PMID 34077310, 2021). "Among them, AKT1 was identified as the core target, while two more active ingredients, luteolin and quercetin in XBJ, have a broad-spectrum effect on COVID-19." (PMID 35185537, 2021). "GO enrichment analysis of the core target AKT1 from the junction targets mapped for the XBJ injection and COVID-19 was conducted using the clusterProfiler package and Cytoscape 3.7.2 was used to plot the results." (PMID 34077310, 2021). "In summary, the activation of IGFR-I and enhanced NOTCH signaling, coupled with altered expression of Bcl2, AKT1, and MAPK8 in severe COVID-19 may lead to an environment that favors cell survival and proliferation." (PMID 39502570, 2024).